HIF1A (hypoxia inducible factor 1 subunit alpha)
Diseases named in the same sentence as HIF1A in open-access papers (continued):
Sharing a sentence is not in itself a finding about the gene and the disease.
esophageal adenocarcinoma (3 papers, 2017 to 2025). A malignant tumor with glandular differentiation arising predominantly from Barrett mucosa in the lower third of the esophagus. "Hypoxia-driven stabilization of HIF1α promotes therapeutic resistance and metastasis in esophageal adenocarcinoma (EAC)." (PMID 41463265, 2025). "A previous study has shown that HIF-1α expression is significantly higher in esophageal adenocarcinoma as compared to Barrett's esophagus, similar to what is observed with CDK 9 in our study." (PMID 28404924, 2017). "Background/Objectives: Hypoxia promotes esophageal adenocarcinoma (EAC) aggressiveness through stabilization of hypoxia-inducible factor-1α (HIF-1α), which regulates pro-survival, pro-metastatic, and immunosuppressive pathways, including the ectoenzyme CD73 (NT5E)." (PMID 41463265, 2025). "In summary, our findings establish that concurrent targeting of HIF1α and CD73 offers a mechanistically integrated, multi-pathway therapeutic strategy for esophageal adenocarcinoma." (PMID 41463265, 2025). "Esophageal adenocarcinoma (EAC) remains difficult to treat, particularly within tumor hypoxic niches that stabilize HIF1α and drive therapeutic resistance and metastasis." (PMID 41463265, 2025). "To examine how hypoxia and inhibition of HIF1α or NT5E influence purine metabolism, we quantified intracellular and extracellular levels of adenosine monophosphate (AMP) and adenosine in FLO-1 esophageal adenocarcinoma (EAC) cells." (PMID 41463265, 2025). "To evaluate the therapeutic relevance of NT5E and HIF1α, we performed siRNA-mediated knockdown experiments in FLO-1 esophageal adenocarcinoma (EAC) cells." (PMID 41463265, 2025). "Utilizing gene expression data from the Cancer Cell Line Encyclopedia, we identified a significant correlation between HIF1A and NT5E gene expression in esophageal adenocarcinoma (EAC) cell lines." (PMID 41463265, 2025). "However, role of HIF-1α in critical cellular processes of esophageal adenocarcinoma is unknown." (PMID 28404924, 2017).
familial cancers (3 papers, 2009 to 2024). "This association confirmed the predominant involvement of HIF-1α in the development of angiogenesis in familial cancers and specifically in BRCA1-2 carrier cancers." (PMID 23326384, 2013). "Our findings also support the role of hypoxia and HIF-1α in the downregulation of ERα expression in familial cancers." (PMID 19724277, 2009). "In addition, we found a positive correlation between MVD and HIF-1α in BRCA1-2 carrier and in all familial cancers, confirming a major aggressiveness of these tumor phenotypes." (PMID 23326384, 2013).
gallstones (3 papers, 2018 to 2022). Solid crystalline precipitates in the biliary tract, usually formed in the gallbladder, resulting in the condition of cholelithiasis. "According to recent research, there appears to be a correlation between hypoxia-inducible factor 1α (HIF1α), gallstone development, and bile changes." (PMID 34440841, 2021). "Researchers also found that patients with NAFLD had increased HIF1α expression in total liver, hepatocytes, and cholangiocytes compared with the healthy subjects, and as a result, they concluded that reduced levels of HIF1α correlate with decreased gallstone formation." (PMID 34440841, 2021). "In addition, liver tissues from patients with NAFLD with gallstones had increased levels of HIF-1α, HMOX1, and VEGFA mRNAs, compared with livers from patients with NAFLD without gallstones." (PMID 29955245, 2018).
gingivitis (3 papers, 2015 to 2025). A disorder involving inflammation of the gums; may affect surrounding and supporting structures of the teeth. "Tissue sections of patients suffering from gingivitis revealed a substantial increase of HIF-1α positive cells." (PMID 25861162, 2015).
glomerular disease (3 papers, 2020 to 2024). "These and the previous mentioned results show that HIF1α is detrimental, whereas EPAS1/HIF2α confers protection in glomerular disease." (PMID 33123011, 2020).
glucose metabolism disorder (3 papers, 2021 to 2024). "Our findings demonstrated that CAT treatment improved TP-induced hepatic glucose metabolism disorder and oxidative stress by modulating the SIRT1/HIF-1α pathway." (PMID 39113710, 2024).
HELLP syndrome (3 papers, 2023 to 2025). A life-threatening condition that can potentially complicate pregnancy. "In this study, we investigated the immunohistochemical staining of SRY-box transcription factor 9 (SOX9) and Hif-1α expression in placentas of pregnant woman with hemolysis, elevated liver enzymes and low platelets (HELLP) syndrome." (PMID 37878989, 2023). "In the placenta with HELLP syndrome, Hif-1α expression was positive in small decidual cell nuclei, but mainly positive in inflammatory cells in the maternal region." (PMID 37878989, 2023). "The aim of this study was to investigate SOX9 and Hif-1α expression of in placentas of women with HELLP syndrome by immunohistochemical methods." (PMID 37878989, 2023). "Furthermore, HIF-1α overexpression reportedly induces a Hemolysis, Elevated Liver enzymes and Low Platelets (HELLP) syndrome-like phenotype and fetal growth restriction in pregnant mice." (PMID 39152497, 2024).
hepatitis C virus infection (3 papers, 2017 to 2023). A viral infection caused by the hepatitis C virus. "For the first time, our present study has demonstrated that VHL expression is dramatically inhibited in human hepatitis C, alcoholic, and cholestatic cirrhotic livers compared with healthy liver samples and that this expression is concomitant with HIF-1α and HIF-2α accumulation." (PMID 28112200, 2017).
Huntington disease (3 papers, 2016 to 2025). Huntington disease (HD) is a rare neurodegenerative disorder of the central nervous system characterized by unwanted choreatic movements, behavioral and psychiatric disturbances and dementia. "The activation of HIF-1α in various neural cells is critical for the generation of reactive oxygen species, underscoring its pivotal role in the pathogenesis of Huntington’s disease." (PMID 38918688, 2024).
hypertensive nephropathy (3 papers, 2021 to 2025). Kidney damage that results from chronically elevated blood pressure; complications include glomerular damage resulting in proteinuria and hematuria. "The present study demonstrated the effects of QYYY on the progress of hypertensive nephropathy and we investigated the underlying mechanisms involved in HIF-1α/PKM2 positive feedback." (PMID 34168560, 2021). "The results suggest that HIF-1α is the up-stream in the metabolic reprogramming and plays a very important role in hypertensive nephropathy." (PMID 34168560, 2021). "Therefore, we speculated that QYYY may affect hypertensive nephropathy via metabolic reprogramming mediated by HIF-1α/PKM2 positive feedback." (PMID 34168560, 2021).
idiopathic pulmonary arterial hypertension (3 papers, 2022 to 2024). A sporadic form of pulmonary arterial hypertension (PAH) characterized by elevated pulmonary arterial resistance leading to right heart failure. "In human idiopathic pulmonary artery hypertension, HIF1-α, HIF2-α, PDGF-B, and autophagy-mediating gene products, including Beclin1, were upregulated in pulmonary artery SMCs and/or lung lysates." (PMID 38652543, 2024). "Researchers have shown that cultured ECs obtained from patients with idiopathic pulmonary arterial hypertension (IPAH-ECs) have a greater HIF-1α expression." (PMID 35203550, 2022). "Previously, it has been reported that ECs isolated from patients with idiopathic pulmonary arterial hypertension (IPAH-ECs) have increased HIF-1α expression." (PMID 38139362, 2023).
Immunodeficiency (3 papers, 2017 to 2023). Failure of the immune system to protect the body adequately from infection, due to the absence or insufficiency of some component process or substance. "If HIF-1α is the cause of impaired glycolytic activity and therefore immune deficiency in HHT patients, then enhancing HIF will lead to improved energy metabolism and potentially an improved immune response in HHT patients." (PMID 37629565, 2023). "We postulate that the decreased HIF-1α accumulation in HHT leads to a clinically observed immunodeficiency in these patients." (PMID 37629565, 2023).
intestinal tumor (3 papers, 2013 to 2022). "Interestingly, the weak association between SUV and HIF1α expression in intestinal tumors was substantially stronger in non-intestinal tumors." (PMID 23718763, 2013). "In a murine intestinal tumor model, myeloid HIF1α deletion has been shown to reduce tumor formation, likely in a non-canonical and hypoxia-indpendent manner." (PMID 36291563, 2022). "We have previously shown that PAK1 expression and activity were increased, and positively correlated with the levels of HIF-1α and β-catenin, in intestinal tumours in APC∆14/+ mice." (PMID 28629331, 2017). "PCNA and HIF1α expression increased three-fold in intestinal tumors (P < 0.01) compared to normal mucosa." (PMID 23718763, 2013).
intrahepatic cholangiocarcinoma (3 papers, 2022 to 2025). A carcinoma that arises from the intrahepatic bile duct epithelium in any site of the intrahepatic biliary tree. "TPI1, also named ETS proto-oncogene 1 (ETS1), works as a downstream transcription factor of HIF-1a, which increases in a hypoxic environment and is highly correlated with recurrence rate of intrahepatic cholangiocarcinoma patients." (PMID 35406597, 2022). "In intrahepatic cholangiocarcinoma (ICC), in vitro assays confirmed its ability to suppress cell proliferation and inhibit epithelial–mesenchymal transition (EMT) through modulation of the HIF-1α-mediated TGF-β1/p-Smad3 signaling pathway." (PMID 41154606, 2025).
iron overload (3 papers, 2022 to 2024). "Taken together, the potential links of the key genes HIF-1α and DMT1 for iron overload, as well as the IL-6R/JAK/STAT pathway that affects aortic iron content and metabolism, are the focus of this research." (PMID 39247821, 2024).
keratitis (3 papers, 2013 to 2021). A corneal disease that is characterized by inflammation of the cornea. "Moreover, in a model of keratitis induced by Pseudomonas aeruginosa, silencing of HIF1α led to increased bacterial growth." (PMID 34393650, 2021).
latent infection (3 papers, 2013 to 2026). "We recently reported that hypoxia, or HIF-1α expression alone, can promote lytic infection in cells that typically support latent infection under normoxia." (PMID 41805195, 2026). "Kaposi's sarcoma-associated herpesvirus (KSHV) stabilizes hypoxia-inducible factor α (HIF-1α) during latent infection, and HIF-1α reactivates lytic replication under hypoxic stress." (PMID 24278015, 2013).
macular edema (3 papers, 2020 to 2025). "These conditions are characterized by pathological processes, such as angiogenesis, ocular hemorrhage, and macular edema, all associated with elevated β-catenin, HIF-1α, VEGF, angiopoietin-2, and MCP-1 levels." (PMID 40362263, 2025). "In the CRVO combined with macular edema group, HIF-1α mRNA and miR-210 levels in the aqueous humor were positively correlated (r = 0.522, P < 0.05), and they were positively correlated with MCP-1, VEGF and IL-6 levels (P < 0.05)." (PMID 35799735, 2022). "HIF-1α, miR-210 and VEGF were the independent risk factors affecting the occurrence of CRVO combined with macular edema (P < 0.05)." (PMID 35799735, 2022). "In patients with CRVO combined with macular edema, HIF-1α and miR-210 were highly effective in the aqueous humor and positively correlated." (PMID 35799735, 2022). "An increase in HIF-1α mediated transcription under ischemic conditions leads to downstream VEGF upregulation with a range of possible sequelae including macular edema and/or ocular bleeding." (PMID 33167932, 2020). "Furthermore, the AUC of miR-210 in the aqueous humor in diagnosing CRVO combined with macular edema was 0.866, which was smaller than HIF-1α mRNA." (PMID 35799735, 2022). "In patients with CRVO combined with macular edema, HIF-1α mRNA and miR-210 were highly expressed in the aqueous humor, which may play an important role in the occurrence and development of the disease." (PMID 35799735, 2022). "Pearson’s correlation analysis showed that in the CRVO combined with macular edema group, HIF-1α mRNA and miR-210 levels in the aqueous humor were positively correlated (r = 0.522, P < 0.05), and they were both positively correlated with MCP-1, VEGF and IL-6 levels (P < 0.05) (Table-IV)." (PMID 35799735, 2022). "Moreover, the AUC of HIF-1α mRNA in the aqueous humor in the diagnosis of CRVO combined with macular edema was 0.888, with the cutoff value of 1.501 and high diagnostic specificity (95.9%), which indicates that the risk of CRVO combined with macular edema is high when HIF-1α mRNA level > 1.501." (PMID 35799735, 2022). "The levels of HIF-1α mRNA, miR-210, MCP-1, VEGF and IL-6 in the aqueous humor of the CRVO combined with macular edema group were higher than those of the cataract control group (P < 0.05)." (PMID 35799735, 2022). "Correlations of HIF-1α mRNA and miR-210 in the aqueous humor of patients with CRVO combined with macular edema with vasoactive molecule levels." (PMID 35799735, 2022). "The area under the curve (AUC) of HIF-1α mRNA and miR-210 in the aqueous humor in diagnosing CRVO combined with macular edema was 0.888 and 0.866, the specificity was 95.9% and 85.1%, and the sensitivity was 76.9% and 80.0%, respectively." (PMID 35799735, 2022). "The levels of HIF-1α mRNA and miR-210 in the aqueous humor of the CRVO combined with macular edema group were higher than those of the cataract control group (P < 0.05)." (PMID 35799735, 2022).
Mycobacterial infection (3 papers, 2020 to 2021). "Mycobacterial infection can disrupt the ER to prompt ER stress, which can be induced by HIF-1α via activation of the ATF4, CHOP, and CHAC1 genes." (PMID 33535567, 2021). "Zebrafish macrophages show stabilization of Hif1α and il-1β expression following mycobacterial infection." (PMID 32158446, 2020). "HIF-1α is thought to play an important role in immunity to mycobacterial infection." (PMID 33552087, 2020).
myeloproliferative neoplasm (3 papers, 2016 to 2026). A clonal hematopoietic stem cell disorder, characterized by proliferation in the bone marrow of one or more of the myeloid (i.e., granulocytic, erythroid, megakaryocytic, and mast cell) lineages. "Applying the JAK2V617F myeloproliferative neoplasms (MPNs) oncogene-driver model, in which HIF-1α is stabilised in normoxia (20% O2), we sought to determine whether the modality of HIF-1 activation directs its function." (PMID 41629621, 2026). "Moreover, in JAK2V617F-positive myeloproliferative neoplasms, HIF-1α is the primary regulator of GLUT-1 and -3 expression." (PMID 36292613, 2022). "This analysis focused on genes (Srpk2, Hes1, Mtor, Pdp1, Meis1, Gfi1, Foxo3, Stra13, Hif1α, and Cebpε) involved in HSC proliferation; maintenance of quiescence, growth, and stem cell exhaustion; and development of myeloproliferative disorder in young and geriatric mice." (PMID 27366154, 2016).
neovascular age-related macular degeneration (3 papers, 2017 to 2024). "Moreover, in neovascular age-related macular degeneration, under hypoxic conditions, HIF-1α upregulates the expression of CSF-1 in choroidal ECs and CSF-1 expression is mediated by HIF-1α binding to the hypoxia response element in the CSF-1 promoter." (PMID 39457693, 2024). "Increased expression and stabilization of HIFs, resulting from age-related RPE changes and hypoxia, have been detected in tissue from patients with neovascular age-related macular degeneration, and their inhibition (in particular of HIF1α) has previously been pursued as a novel therapeutic strategy." (PMID 37330004, 2023).
nevus (3 papers, 2012 to 2025). Nevus (or naevus, plural nevi or naevi, from nævus, Latin for "birthmark") is the medical term for sharply circumscribed[1] and chronic lesions of the skin or mucosa. "The nuclear expression of HIF‐1α was noted in only 1 case of nevus and a focal pattern." (PMID 40867038, 2025).
odontogenic cyst (3 papers, 2019 to 2025). A cyst in the jaw that arises from tissues of tooth development. "According to previous studies, the expression of HIF-1α in odontogenic cysts and periapical granulomas could be viewed as a cause of the pathology or a response to it." (PMID 39657933, 2025). "The expression of HIF-1α in different odontogenic cysts can provide additional evidence of whether and how hypoxia occurs in these lesions." (PMID 31319505, 2019).
oral lichen planus (3 papers, 2022 to 2026). Oral lichen planus is a chronic inflammatory oral condition of unknown aetiology characterized by T-cell-mediated chronic immune response and abnormal epithelial keratinization cycle. "It had been shown that the HIF1α/PLD2 axis was associated with glycolysis and induces T cell immunity in oral lichen planus." (PMID 35256894, 2022).
ovarian clear cell cancer (3 papers, 2019 to 2022). An invasive malignant neoplasm that arises from the ovary and is characterized by a predominance of clear and hobnail malignant epithelial cells. "Glycogen deposition is not only limited to adipocytes, rather hypoxia induced by HIF-1α has been reported to promote glycogen deposition in human ovarian clear cell carcinoma cells." (PMID 35496046, 2022). "The upregulation of IL-6, STAT3, HIF-1α observed in ovarian clear cell cancer samples indicates an IL-6/STAT3/HIF1α/VEGF autocrine activation loop in EOC thereby facilitating tumor angiogenesis." (PMID 35401182, 2022). "Also, immunohistochemical analysis revealed an increase in the nuclear expression of pY-STAT3 and HIF1α in ovarian clear cell carcinoma." (PMID 35401182, 2022).
Peri-Implantitis (3 papers, 2020 to 2025). An inflammatory process with loss of supporting bone in the tissues surrounding functioning DENTAL IMPLANTS. "Although the present study was the first to assess the TNF-α, IL-10, VEGF, and HIF1-α immune balance in peri-implantitis, it has limitations since we evaluated the local immune response of the peri-implant condition at a given time." (PMID 38477721, 2024). "The study’s findings revealed that individuals with peri-implantitis exhibited significantly elevated levels of HIF-1α compared to the control group, implying a substantial role for hypoxia in the pathogenesis of peri-implant disease." (PMID 38477721, 2024). "However, it is crucial to acknowledge that this study represents the first attempt to correlate TNF-α, IL-10, VEGF, and HIF1-α in peri-implantitis." (PMID 38477721, 2024). "It shows an elevated HIF-1α levels in patients with peri-implantitis, which could have stemmed from persistent inflammation- triggered hypoxia." (PMID 38477721, 2024). "This study, for the first time demonstrates the balance of HIF-1α, TNFα, IL-10, and VEGF in peri-implantitis." (PMID 38477721, 2024). "Patients with peri-implantitis exhibited significantly higher HIF-1α levels than those without peri-implantitis (p=0.0005)." (PMID 38477721, 2024). "Considering these findings, we hypothesized peri-implantitis increases the expression of VEGF, HIF-1α, TNF-α, and IL-10 in the PICF." (PMID 38477721, 2024). "TNF-α revealed significant positive correlations with IL-10 (p=0.0008) and VEGF (p=0.0246), whereas HIF-1α and IL-10 levels (p=0.0041) demonstrated a negative and significative correlation in the peri-implantitis group." (PMID 38477721, 2024). "This study aimed to compare the levels of HIF1-α, VEGF, TNF-α, and IL-10 in the peri-implant crevicular fluid of patients with and without peri-implantitis." (PMID 38477721, 2024). "The authors compared the levels of HIF1-α, VEGF, TNF-α, and IL-10 in peri-implant crevicular fluid between patients with or without peri-implantitis." (PMID 38477721, 2024).